IL6 (interleukin 6)
Diseases named in the same sentence as IL6 in open-access papers (continued):
Sharing a sentence is not in itself a finding about the gene and the disease.
periodontitis (continued). "Increased plasma levels of IL-1β, IL-6, TNF-α, CRP, MMP-8, and MMP-9 have been observed in patients with periodontitis." (PMID 38672972, 2024). "Levels of IL-6, LDH, and CRP in those suffering from chronic periodontitis compared to healthy controls were checked." (PMID 38595889, 2024). "In another induced periodontitis in a diabetic rat experiment, Cu reduced the infiltration of PMN and monocytes, the degradation of periodontal collagen fibers—and decreased IL-1β, IL-6, TNF-α MMP-9 and MMP-2, MMP-8 levels." (PMID 38793109, 2024). "The effects of anti-infective treatment (scaling and root planning) in 13 periodontitis patients were monitored by aMMP-8, the rate of aMMP-8 RFU activity, tMMP-8, MPO, PMN elastase, TIMP-1, calprotectin, and IL-6 as well as by clinical periodontal parameters." (PMID 39273368, 2024). "Chronic periodontitis patients show an increase in the TNF-α, IL-6, IL-1B, and RANK-L levels and a decrease in OPG." (PMID 38817441, 2024). "The combination of MMP-8, IL-1β, IL-6, and MIP-1α has shown promise in distinguishing between gingivitis and periodontitis, although based on a smaller study sample." (PMID 39554809, 2024). "A recent systematic review highlights several biomarkers, including macrophage inflammatory protein-1 alpha (MIP-1α), IL-1β, IL-6, and MMP-8 (matrix metalloproteainase-8), as promising indicators for diagnosing periodontitis." (PMID 39917647, 2024). "Osteocalcin (OC), IL-1β, tumor necrosis factor-alpha (TNF-α), interleukin-6 (IL-6), OPG, and matrix metalloproteinase-9 (MMP-9) were significant in oral fluid or saliva, and they were from periodontitis, MRONJ, and osteoporosis." (PMID 39410587, 2024). "Among the many immunological mediators secreted during inflammatory processes, several pro‐inflammatory interleukins (IL‐1, IL‐6, IL‐8) and tumor necrosis factor‐alpha (TNF‐α) have been extensively studied for their possible systemic presence in periodontitis." (PMID 39494478, 2024). "CBD administered in animals subjected to experimental periodontitis and in cells stimulated by LPS from P. gingivalis reduced the levels of cytokines such as RANK, RANKL, TNF- α, IL-1β, IL-6, IL-12 p40, and IL-8." (PMID 39065590, 2024). "The study underscored a clear link between higher levels of IL-6, LDH, and CRP and the presence of chronic periodontitis in pregnant women." (PMID 38595889, 2024). "The increased mRNA expression of IL-1β and IL-6 in the PBS group suggested the activation of M1 macrophages and an abundance of inflammatory cytokines in periodontitis." (PMID 39076893, 2024). "This cross-sectional clinical study assessed the GCF concentrations of IL-6, IL-17, and IL-35 in both healthy controls and participants with severe and advanced stages (S III-S IV) of periodontitis." (PMID 39215253, 2024). "Recent studies have suggested potential links between periodontitis during pregnancy and systemic inflammatory markers such as CRP, IL-6, and TNF-α." (PMID 38595889, 2024). "The hub genes identified in the periodontitis comorbidity network, such as TNF, IL6, PTGS2, IL10, and NOS3, play pivotal roles in connecting periodontitis with various systemic diseases, as indicated by their high connectivity degrees." (PMID 39337647, 2024). "The results showed that in both periodontitis groups, there was a strong positive correlation between ACE2 and IL-6." (PMID 39917640, 2024). "Recent studies have explored the potential impact of periodontitis during pregnancy on systemic inflammatory markers such as CRP, IL-6, and tumor necrosis factor-alpha (TNF-α)." (PMID 38595889, 2024). "It specifically focuses on the levels of interleukin-6 (IL-6), lactate dehydrogenase (LDH), and C-reactive protein (CRP) in those suffering from chronic periodontitis compared to healthy controls." (PMID 38595889, 2024). "Increased levels of salivary IL-1β, IL-6, and MMP-8 were observed in individuals with periodontitis." (PMID 39410587, 2024).
periodontitis (continued). "The presence of IL-6 in saliva and GCF highlights its role in the development and progression of aggressive periodontitis." (PMID 39125970, 2024). "In the present study, elevated levels of IL-1β, IL-6, and TNF-α were observed in the periodontitis group, indicating an inflammatory response mediated by inflammatory cells during disease progression." (PMID 38919285, 2024). "Inflammatory cytokines, including IL-1β, IL-6, tumor necrosis factor-alpha, and chemokine (C-C motif) ligand 2 (CCL2), play a crucial role in the inflammatory response of periodontitis." (PMID 38560458, 2024). "In conclusion, moderate certainty evidence shows that NSPT has a positive effect on the reduction of IL-6 and SBP in patients with periodontitis, while low certainty evidence shows that NSPT is effective for reduction of CRP." (PMID 38877442, 2024). "Meanwhile, elevated GCF levels of IL-6 and RANKL were observed in patients with both chronic periodontitis and osteoporosis, compared to controls, indicating an active bone resorption process." (PMID 39410587, 2024). "IL-1β, IL-6, TNF-α and IFN-γ have been identified as key players in the pathogenesis of periodontitis." (PMID 38002398, 2023). "Our previous study found that 3 months of PG treatment elevates GCF levels of IL-6 and TNF-α in women with periodontitis." (PMID 37645411, 2023). "HGFs stimulated with pathogens have been reported to upregulate the gene expression of the pro-inflammatory cytokines IL-6, IL-1β, IL-8, and TNF-α, which facilitates the inflammatory cascade in periodontitis." (PMID 37110385, 2023). "Thus, inflammatory mediators such as C-reactive protein (CRP), tumor necrosis factor -α (TNF-α) and interleukin-6 (IL-6) may be the link between periodontitis and hypertension, and smoking may promote the co-occurrence and development of the two diseases as a common risk factor." (PMID 37308938, 2023). "Subsequently, the inflammatory cytokines expression levels (interleukin-IL-6, IL-1β, IL-8, and IL-10) in EXO-NET EVs were measured for non-periodontitis and periodontitis." (PMID 39697803, 2023). "Patients with periodontitis have higher levels of inflammatory biomarkers such as CRP and interleukin-6 in both gingiva and serum." (PMID 38021744, 2023). "Periodontitis has been shown to increase levels of proinflammatory cytokines such as TNF-alfa, IL-1 and IL-6." (PMID 37767526, 2023). "The pro-inflammatory cytokines IL-6, IL-33 and IL-17A can be proposed as biomarkers of both conditions in GCF due to their ability to trigger the activation of osteoclastogenesis in periodontitis." (PMID 36967976, 2023). "In conclusion, our results demonstrated, through meta-analytic methods with 1,983 participants from 9 studies, that IL-6, nitric oxide, IL-1B, TNF-α and osteoprotegerin are among the most present biomarkers in patients with periodontitis." (PMID 37026605, 2023). "In RA and periodontitis, adaptive and innate immune cells promote the release of proinflammatory cytokines (TNF-α, IL-6, IL-17A, IL-1β, RANKL), which have an important role in establishing and maintaining inflammation." (PMID 37217496, 2023). "In vivo test using a rat periodontitis model treated with glycyrrhizin revealed the downregulation of HMGB1, IL-6, and IL-1β in the gingival crevicular fluid and periodontal tissue." (PMID 37396128, 2023). "PBMC cells from periodontitis subjects released higher levels of TNF‐a and IL‐6 than those from healthy subjects after Escherichia coli lipopolysaccharides stimulation." (PMID 37506160, 2023). "There was a higher prevalence of stage III periodontitis and severe OSA, as well as higher levels of periodontal parameters (PI and BOP), and expression of IL-1β and IL-6 in saliva and IL-6, IL-17A, and IL-33 in GCF, in patients with periodontitis and OSA." (PMID 36967976, 2023).
periodontitis (continued). "Higher salivary IL6 and IL8 levels were also reported in patients with OSCC compared to other inflammatory oral diseases, including chronic periodontitis and oral lichen planus, in addition to healthy controls in a cohort from USA." (PMID 36900301, 2023). "A recent systematic review and meta-analysis suggests MIP-1α IL-1β, IL-6, and MMP-8 as highly sensitive salivary markers of periodontitis." (PMID 38068492, 2023). "The combination of NK357 with NK391 (NKc) additively decreased PG 16S rDNA levels as well as suppressed PG-induced periodontitis: they suppressed TNF-α and IL-6 expression and GP+LPS+ and NF-κB+CD11c cell populations in the periodontal tissue." (PMID 36904068, 2023). "Periodontal bacterial and related endotoxins, present during periodontitis, trigger systemic inflammation, as revealed by the increased levels of CRP, TNFα, IL-1β, and IL-6 in the serum of patients." (PMID 37895050, 2023). "The chronic periodontitis population with CAD had the majority of CC, AA, and TT genotypes in IL-6 -572 C/G, CRP -757 A/G, and CRP -717 T/C C/G gene polymorphisms." (PMID 37239434, 2023). "Related research reported that stem cells from human exfoliated deciduous teeth (SHED)-derived CEVs (SHED-EVs) reduced IL-6 and TNF-α expression in lipopolysaccharide (LPS)-induced inflammatory BMMSCs, and in tissues from the defect area of periodontitis mice." (PMID 36982864, 2023). "Interleukin 6 (IL-6) and C-Reactive Protein (CRP) play an important role in chronic periodontitis with coronary artery disease (CAD)." (PMID 37239434, 2023). "The expression levels of four inflammatory cytokines, IL-6, IL-10, IL-8, and IL-1β, were evaluated in salivary EXO-NET EVs of non-periodontitis and periodontitis patients using ELISA." (PMID 39697803, 2023). "IL-6, in turn, can stimulate and release more CRP, which can exacerbate the development of periodontitis by accumulating in the gingival crevicular fluid." (PMID 37481511, 2023). "It has been reported that gingival fibroblasts express cGAS and STING and produce various inflammatory cytokines, including IL-6, IL-8, and CCL2, in periodontitis." (PMID 37405166, 2023). "The levels of IL-6, IL-1β, TNF-α, and IFN-β secreted under the influence of P. gingivalis were lower in the StingGt periodontitis mice than in the WT periodontitis mice (p < 0.05)." (PMID 37405166, 2023). "Alternatively, in patients with chronic periodontitis and chronic systemic diseases, higher levels of inflammatory cytokines are observed, including TNF-α, IL-1, and IL-6." (PMID 37481511, 2023). "Initially, to ensure the reliability of the samples, inflammatory cytokines including IL-1β, IL-6, and TNF-α of each group were evaluated by RT-qPCR, all of which are significantly upregulated in periodontitis." (PMID 37261283, 2023). "It exhibits a number of direct actions in periodontal tissues, such as stimulating immune response cells to synthesize other cytokines (interleukin-6, interleukin-8, TNF and G-CSF) that are involved in the development of periodontitis." (PMID 37510729, 2023). "Common inflammatory phenotypes in oral (e.g., periodontitis) can stimulate the increase in circulating inflammatory factors such as CRP, Interleukin-1, Interleukin-6, and Interleukin-8 as well." (PMID 37978427, 2023). "The aim of the present study was to investigate any shifts in personalized antimicrobial peptide (LL-37) and cytokine (IL-4, IL-6 and IL-10) profiles in GCF in periodontitis patients subsequent to SRP." (PMID 37246231, 2023). "Bahammam and Attia have found significantly elevated levels of IL-6, TNF-α, and visfatin in GCF of diabetic patients afflicted with chronic periodontitis." (PMID 38149100, 2023). "In this study, SRP significantly decreased the GCF levels of IL-6 and TNF-α, which supports the anti-inflammatory effect of SRP in periodontitis." (PMID 37645411, 2023).
periodontitis (continued). "The association between AS and periodontal diseases is supported by the detection of pronounced increases in serum interleukin (IL)-6 and tumor necrosis factor-alpha (TNF-α) levels between the immunopathological state in AS and periodontitis." (PMID 37875827, 2023). "Periodontitis results in the formation of cytokines, most distinctively, tumor necrosis factor-alpha (TNF-α), interleukin (IL)-1, and IL-6/." (PMID 37102031, 2023). "Compared with 10% glucose, treatment with 0.1% stevioside reduced alveolar bone absorption and osteoclasts while decreasing IL-6, TNF-α, IL-1β, and P. gingivalis in the gingiva of periodontitis mice." (PMID 37563632, 2023). "Enhanced RANKL production and NF-κB signaling pathway activation by pro-inflammatory mediators, including IL-6, TNF-α, IL-1β, prostaglandin E2 (PGE2) and C3 are common in inflammatory diseases, including periodontitis and osteoporosis." (PMID 36359775, 2022). "According to a 2014 meta-analysis of interventional trials, treatment of periodontitis generally leads to significant decreases in serum levels of CRP, IL-6, TNF-α, fibrinogen, total cholesterol, and a significant rise in HDL-cholesterol." (PMID 35200242, 2022). "Other studies have explored the methylation levels of other potential targets, such as IL6 and tet-methylcytosine dioxygenase 2 (TET2) enzymes, and observed partial methylation of periodontitis tissues with increased levels of gene expression." (PMID 36291079, 2022). "Members of the IL-1, IL-6, and TNF families are key proinflammatory cytokines involved in periodontitis." (PMID 35845957, 2022). "Apart from IL-6, TNF-α is a typical inflammatory cytokine in periodontitis that directly stimulates osteocytes to produce RANKL and induce osteoclastogenesis or promote sclerostin expression in osteocytes leading to increased osteoclastogenesis." (PMID 35628348, 2022). "This is characterized by production of numerous mediators like IL-1β, IL-6, IL-8, and TNF-α, which are also involved in the progression of periodontitis." (PMID 34185172, 2022). "NSPT has a positive effect on the reduction of serum CRP level in patients of CAD with periodontitis, while limited evidence was obtained that NSPT can positively affect the variation of IL-6, FMD and lipid metabolism parameters." (PMID 36243997, 2022). "Within the periodontium, IL-1, IL-6, and TNF-α levels are enhanced in patients with both DM and periodontitis compared to patients with periodontitis alone and there is a direct relationship between cytokine levels and glucose control." (PMID 35052857, 2022). "Many inflammatory cytokines, such as interleukin (IL)-1, IL-6, IL-17, and tumor necrosis factor (TNF)-α, play an important role in the pathogenesis of periodontitis." (PMID 36289921, 2022). "Recent systematic reviews focused on IL-1beta, IL-6 and MMP-8 as promising candidates for early diagnosis of periodontitis." (PMID 35327490, 2022). "Patients with periodontitis stage III grade B and grade C had statistically higher levels of IL-1 and IL-6 than healthy participants (p < 0.05)." (PMID 35368315, 2022). "The aim of this study was to investigate the anti-inflammatory effects of DJLE by evaluating the inhibition of IL-1β, IL-6, TNF-α, iNOS, and COX-2 expression in hPDLCs to examine the potential to develop a treatment agent for periodontitis." (PMID 35455384, 2022). "Elevated systemic inflammatory cytokines, such as Interleukin-1β (IL-1β), Interleukin-6 (IL-6), C-Reactive protein (CRP), and Tumor necrosis factor-α (TNF-α), were attributable to periodontitis have been documented by previous studies." (PMID 35162556, 2022). "Especially, P. gingivalis-LPS is a strong virulence factor in periodontitis and induces cytokine secretion (TNF-α, IL-6, and MCP-1) and inflammatory responses via TLRs." (PMID 35564380, 2022). "We also found serum from periodontitis patients had a smaller effect on TNF-α and IL-6 levels than saliva." (PMID 36207325, 2022).
periodontitis (continued). "The effect of periodontitis and/or orthodontic tooth movement (OTM) on alveolar bone and gingival IL-6 and CXCL2 expressions was studied in rats by histology and RT-PCR, respectively." (PMID 34024010, 2022). "In periodontitis, inflammation-inducing factors, such as TNF-α, IL-1β, and IL-6, are secreted from PDL cells due to bacterial endotoxin release, causing periodontal inflammation and infection." (PMID 36145616, 2022). "A research study investigated IL-1β, IL-6, MMP-8, and IL-10 levels in healthy as well as periodontitis patients and found that IL-1β and IL-6 concentrations were significantly higher in periodontitis patients." (PMID 36289921, 2022). "Proinflammatory cytokines IL-1β, IL-6, and TNF-α are present in osteoclast precursor cells and mature osteoclasts, and it mediates bone resorption in periodontitis." (PMID 35757444, 2022). "iPTH decreases local levels of IL-6, MMP-2 and MMP-9 in Wistar rats with experimental periodontitis." (PMID 36359775, 2022). "Patients with severe periodontitis have increased levels of pro-inflammatory markers (CRP, fibrinogen, IL-6, IL-1, TNF-α) and neutrophils in the blood and effective periodontal treatment diminishes these inflammatory markers." (PMID 35052857, 2022). "PPARα agonist decreased gingival mRNA levels of IL-1, IL-6, TNF-α, and RANKL/OPG in ligatures-induced experimental periodontitis." (PMID 35293424, 2022). "In models of periodontitis, fucoxanthin was shown to inhibit the promotion of osteoclast differentiation and reduce TNF, IL-1β, and IL-6 levels in blood." (PMID 36501023, 2022). "A similar COVID-19 cytokine dysregulation, in particular of IL-1beta, IL-6, IL-10, IFN-γ, TNF-alfa and Transforming Growth Factor (TGF)-beta, was found in patients who presented psychiatric disorders, periodontitis and peri-implant disease." (PMID 35323251, 2022). "The results showed that patients with periodontitis presented significantly more inflammatory mediators, such as TNF-α, IL-6, IL-8, ADMA, Galectin-3, in comparison with healthy subjects." (PMID 35473620, 2022). "The qRT-PCR results revealed upregulation of IL-1β, IL-6 and ALOX5 in the periodontitis group and further upregulation in the periodontitis with T2DM group, while the expression of NFE2L2 was the opposite." (PMID 36248844, 2022). "Compared with the control group, the mRNA expression levels of IL-1β, IL-6 and ALOX5 were increased in the periodontitis group and further increased in the periodontitis with T2DM group." (PMID 36248844, 2022). "In a rat model of experimental periodontitis, treatment with fucoxanthin led to a decrease in blood levels of TNF-α and IL-6." (PMID 35327570, 2022). "The IL-6 and CXCL2 levels were also studied in human gingival biopsies from periodontally healthy and periodontitis subjects by RT-PCR and immunohistochemistry." (PMID 34024010, 2022). "In Pg-LPS-induced periodontitis, macrophages regulate the inflammatory response by producing a variety of proinflammatory mediators such as TNF-α, IL-6, and IL-1β." (PMID 35340409, 2022). "Regarding individual biomarkers, IL-1β, IL-6, and MMP-8 levels were significantly higher in periodontitis patients (p ≤ 0.001, p < 0.05, respectively)." (PMID 35368315, 2022). "Hs-CRP and IL-6 were dramatically increased in patients with NBP and hypertension compared with patients with periodontitis only (P < 0.05)." (PMID 35813436, 2022). "In contrast, however, immunostaining against IL-6 and CXCL2 proteins was more pronounced in the biopsies of periodontitis patients." (PMID 34024010, 2022). "Periodontitis patients have been shown to have elevated blood levels of pro-inflammatory markers, such as C reactive protein (CRP), fibrinogen, IL-6, interleukin-1 (IL-1), and TNF-α." (PMID 36015357, 2022).